IGFBP2 (insulin like growth factor binding protein 2)
Diseases named in the same sentence as IGFBP2 in open-access papers (continued):
Sharing a sentence is not in itself a finding about the gene and the disease.
glioma (continued). "Strong correlation between the expression of IGFBP2 mRNA and these biomarkers in GBM suggested that IGFBP2 may play an important role in the development or progression of glioma." (PMID 31138764, 2019). "Functionally, IGFBP2 has been established as a driver of glioma progression to a higher grade." (PMID 31296788, 2019). "As for its differential expression pattern on the three glioma subtypes, IGFBP2 has been confirmed to be highly expressed in gliomas with high malignancies, such as glioblastoma and anaplastic astrocytoma, but expressed low in the relatively binary astrocytoma, the diffuse astrocytoma." (PMID 30322114, 2018). "Therefore, IGFBP2, EGFR_pY1068, HER2_pY1248, and EGFR_pY1173 are affected in the same way by IDH1 mutations in low-grade glioma and glioblastoma, and we report a cross-cancer effect for those groups." (PMID 30442178, 2018). "Although many genes identified in this study may serve as prognostic markers of lower-grade gliomas, only IGFBP2 remains prognostic within IDH-mutant glioma patients." (PMID 27852048, 2017). "Enhanced gene expression of IGFBP1 and IGFBP2 has been demonstrated in meningiomas and gliomas." (PMID 28786923, 2017). "Moreover, NFIA-regulated IGFBP2 signaling pathways play a critical role in the ability of miR-302b to regulate apoptosis in glioma cells." (PMID 28323865, 2017). "Furthermore, within the IDH-mutant group, IGFBP2 was the only gene that was still prognostic at the mRNA levels; the median overall survival of IDH-mutant gliomas with high IGFBP2 expression was ~25% worse than that of IDH-wildtype." (PMID 27852048, 2017). "However, numerous studies have suggested that IGFBP2 contributes to carcinogenesis, particularly that of gliomas." (PMID 28323865, 2017). "Taken together, these results indicate that although IGFBP2 expression is low in IDH-mutant gliomas of all three histological types, the increased expression is a powerful, negative prognostic marker that predicts a median overall survival worse than that of IDH-wildtype group." (PMID 27852048, 2017). "It is also reported that in IDH-mutant glioma, IGFBP2 was inhibited so that patients’ survival could be improved." (PMID 29050331, 2017). "Consequently, our data suggest that NFIA enhances the IGFBP2 signaling pathway, resulting in glioma tumorigenesis." (PMID 28323865, 2017). "IGFBP-2 plays critical roles in resistance to chemotherapy in many malignant tumors, such as breast cancer, esophageal adenocarcinoma, colon cancer, lung cancer, prostate cancer, glioma and leukemia." (PMID 28977895, 2017). "Overexpression of the IGFBP2 protein promotes glioma stem cell survival and glioma progression." (PMID 28323865, 2017). "Re-expression of miR-491 in glioma cells and GSCs suppressed IGFBP2, and impaired many of the tumorigenic phenotypes (cell proliferation, invasion, and stem cell maintenance), which have been previously attributed, at least in part, to high levels of IGFBP2." (PMID 26682264, 2015). "Notably, IGFBP2 has been connected to both hematopoietic and glioma stem cell expansion and survival." (PMID 26097693, 2015). "Notably, the proteolytic pattern of IGFBP2 was also detected in human glioma culture cells and, more importantly, in all glioma samples evaluated." (PMID 24962328, 2014). "Using gene expression public databases, we confirmed that IGFBP2 is a poor prognosis marker for gliomas, and we also observed an important contribution of ADAMTS1.Finally, we showed the impact of ADAMTS1 on IGFII-mediated IGF1R phosphorylation and cellular migration." (PMID 24962328, 2014). "The use of IGFBP2 as a prognostic factor in identifying glioma requires further investigation." (PMID 24962328, 2014). "While genomic studies have strongly suggested the expression of IGFBP2 to be used as a bad prognosis factor in glioma, our studies support for the first time, at least to our knowledge, the need to analyze the cleavage of IGFBP2 protein in human glioma specimens." (PMID 24962328, 2014).
glioma (continued). "The prognostic value of plasma IGFBP-2 after postoperative combined radiotherapy and chemotherapy in glioma patients is unknown." (PMID 24690948, 2014). "Our studies do not exclude other proteases to be the cause of IGFBP2 cleavage in gliomas and, in fact, we consider this a relevant field of study." (PMID 24962328, 2014). "Indeed, the IGFBP2/integrin/ILK/NF-kB network was recently reported to be a key player in glioma progression and poor outcomes." (PMID 24069370, 2013). "Moreover, elevated serum or plasma IGFBP2 levels have been observed in patients with glioma, prostate cancer, ovarian cancer, and colon cancer." (PMID 24069370, 2013). "For example, IGFBP2 has anti-apoptotic effects in multiple types of solid cancer, binds to integrin α5 resulting in migration of Ewing’s sarcoma cells, and activates integrin β1 to induce glioma cell motility." (PMID 24191913, 2013). "Indeed, IGFBP2 is overexpressed in the tumor tissues of glioma, breast cancer, ovarian cancer, prostate cancer, colorectal cancer, gastric cancer, lung cancer, leukemia, and astrocytoma." (PMID 24069370, 2013). "Interestingly, our study suggested different results in lung cancer, indicating a different immunogenicity of IGFBP-2 in patients with lung cancer compared to patients with gliomas and colorectal carcinoma." (PMID 23165420, 2013). "Further, IGFBP2 enhances glioma cell invasion by increasing invasion-related genes including MMP2." (PMID 15686601, 2005). "While further studies are needed to directly assess Igfbp2 expression in human MTLE tissue using non‐tumor controls, elevated Igfbp2 levels have been observed in disorders with an increased risk of epilepsy, including Alzheimer's disease, multiple sclerosis, and gliomas." (PMID 41239819, 2026). "IGFBP2 could also serve as a biomarker for diagnosing and monitoring the progression of gliomas." (PMID 37928523, 2023). "Additionally, glioma-derived IGFBP2 was observed to enhance microglial migration." (PMID 37928523, 2023). "Our study revealed that glioma-derived IGFBP2 could facilitate the migration of macrophages." (PMID 37928523, 2023). "Therefore, it might be an effective treatment for glioma patients by inhibiting IGFBP2 mediating the integrin β1/ERK signaling pathway, in combination with chemotherapy." (PMID 35546443, 2022). "Therefore, the prognosis of IGFBP2 in underlying mechanism should be explored, and whether pathways of IGFBP2 mediated are helpful in treatment of glioma and colorectal cancer patients needs to be confirmed through more fundamental research." (PMID 35546443, 2022). "Finally, the importance of IGFBP2 in TCGA-glioma cohort was confirmed." (PMID 36110851, 2022). "Therefore, IGFBP2 is highly likely to be the oncogenic gene of glioma." (PMID 36110851, 2022). "Indeed, miR-204-3p and miR-491-3p inhibit IGFBP-2 expression and are downregulated in glioma cells." (PMID 33604294, 2020). "Therefore, IGFBP2 may be another potential biomarker for the distinction of the three glioma subtypes with positive IDH-1." (PMID 30322114, 2018). "Low IGFBP2 expression seems attributable to global DNA hypermethylation, but the regulatory mechanism seems complex with the possible involvement of copy number (data not shown); thus, further investigations are warranted to understand how IGFBP2 becomes deregulated to drive glioma progression." (PMID 27852048, 2017). "Consequently, a comprehensive understanding of the molecular pathways regulated by IGFBP-2 gene expression in gliomagenesis may facilitate the development of glioma therapies." (PMID 28323865, 2017). "Moreover, exogenous IGFBP-2 has been shown to exhibit chemoresistance to TMZ in glioma cells." (PMID 28977895, 2017). "A recently published paper first demonstrated that serum anti-IGFBP-2 antibody was significantly elevated in gliomas and colorectal carcinoma, suggesting that the detection of circulating anti-IGFBP-2 antibody may be a potential approach in diagnosing early cancers." (PMID 23165420, 2013).
glioma (continued). "Other fc3 genes in the curated set, FERMT1, TMEM100, DYNLT3, EPHB1, IGFBP2, NNMT, and SH3GL2 all show direct evidence to a relationship with glioma biology and patient prognosis." (PMID 39941811, 2025). "We established and validated a robust four-gene signature (MAOB, IGFBP2, SERPINA1 and LGR6) that serve as an independent prognostic biomarker for grade II/III gliomas." (PMID 40821817, 2025). "Therefore, further to previously delineated observations of IGFBP2 overexpression in tumour tissue and immortalised cell lines, emerging evidence suggests additional roles for the maintenance of glioblastoma cells with stem cell properties—commonly referred to as glioma stem cells (GSCs)." (PMID 40429889, 2025). "Further molecular profiling of 1122 diffuse glioma samples by Ceccarelli and colleagues in 2016 revealed IGFBP-2 protein elevation in glioblastoma with EGFR, P-EGFR and P-Akt, when compared with lower-grade gliomas (2016 CNS WHO grades II and III)." (PMID 40429889, 2025). "By identifying differentially expressed genes (DEGs) between subtypes, we constructed a four-gene prognostic signature (MAOB, IGFBP2, SERPINA1, and LGR6) and validated its robustness using the Chinese Glioma Genome Atlas (CGGA) expression dataset." (PMID 40821817, 2025). "Its predictive power for survival aligns with the roles of these genes in glioma biology: CHI3L1 promotes invasiveness via NF-κB activation, while IGFBP2 enhances angiogenesis through IGF signaling." (PMID 40535771, 2025). "In comparison to other glioma subtypes, the GS2 exhibited higher expression levels of IBSP, PLA2G2A, NNMT, CA9, and MMP9, while the GS5 showed higher expression levels of CHI3L1, IGFBP2, EMILIN3, MEOX2, and PDPN." (PMID 38332637, 2024). "HOTAIRM1 can positively regulate IGFBP2 expression, and IGFBP2 binds with HOTAIRM1 via METTL3-mediated m6A binding-domains and increases its stability and expression in glioma tissues and cells." (PMID 39691597, 2024). "In gliomas, SMOC1, S100A6, CTSB, SPP1, and IGFBP2 serve as a potential therapeutic target in glioma." (PMID 39530009, 2024). "The violin plot demonstrated that IGFBP2, SMC4, PLAT, and ANXA1, showed relatively higher expression levels in pericytes and glioma cells compared to other scoring genes." (PMID 39906742, 2024). "We aimed to interrogate the oncogenic effects of IGFBP‐2 and GRP78 in our glioma stem cell (GSC) lines and clinical cohort." (PMID 37212470, 2023). "The result suggested that KCNIP, IGFBP2, IL5, and SAMD9L were independent poor prognostic factors for GBM and glioma." (PMID 36762114, 2023). "Our data showed that HOTAIRM1, post-transcriptionally stabilized by METTL3, bound to IGFBP2, suggesting that HOTAIRM1 promotes VM formation in glioma via up-regulating IGFBP2 expression, providing a theoretical basis for new glioma treatment methods." (PMID 38012763, 2023). "We also noticed that IGFBP2 was downregulated in glioma cells after HOTAIRM1 knockdown and IGFBP2 facilitated HOTAIRM1-triggered glioma cell malignancy and VM formation." (PMID 38012763, 2023). "More recently, a study revealed that IGFBP2 promotes vasculogenic mimicry by modulating CD144 and MMP2 expression in glioma." (PMID 37737709, 2023). "Recent research demonstrated that IGFBP2 activates integrin β1 pathways, recruits ILK for cell migration, and activates NF-κB in glioma." (PMID 37957694, 2023). "IGFBP2 is known to promote EMT in a variety of tumors, including pancreatic ductal adenocarcinoma, glioma, and prostate cancer." (PMID 37029430, 2023). "IGFBP2 induces the proliferation and invasion of glioma cells through the β1/ERK signaling pathway, indicating that IGFBP2 can be used as a potential therapeutic target for gliomas." (PMID 35011220, 2022). "The expression values of AEBP1, F3, FLNC, IGFBP2, and LDHA were compared among normal brain tissue, low-grade gliomas (LGG), and GBM." (PMID 35783254, 2022).
glioma (continued). "Studies have shown that overexpression of IGFBP2 can increase the malignant degree of glioma and up-regulate the expression of invasion protein MMP2, thereby enhancing the invasion ability of glioma cells." (PMID 36110851, 2022). "The results from the Oncomine database showed that IGFBP2, IGFBP3, IGFBP4, and IGFBP5 were expressed at a higher level in tissues from patients with brain and CNS cancer than in normal tissues from healthy individuals." (PMID 35832140, 2022). "Using the polymerase chain reaction, GBM cell lines were found to express mRNA for IGFBP genes: IGFBP-1 in 42%, IGFBP-2 in 65%, IGFBP-3 in 97%, IGFBP-4 in 3%, IGFBP-5 in 74%, IGFBP-6 in 94%, and IGFBP-7 in 87% of glioma cell lines." (PMID 35832140, 2022). "Based on the data from the Oncomine database, the transcriptional levels of IGFBP2, IGFBP3, IGFBP4, and IGFBP5 were observed to be elevated in brain and CNS cancer." (PMID 35832140, 2022). "IGFBP2 contains an RGD motif through which it binds to integrin and affects cell proliferation and survival in high-grade glioma and hepatocellular carcinoma." (PMID 34572779, 2021). "A series of genes such as EN1, S100A4, ANXA1, PDPN, IGFBP2 and CHI3L1 were upregulated in radiotherapy treated glioma patients, while other genes such as PRLHR, SFRP2, BRINP1, TRIM67, LHX5, KCNIP2 and NSG2 were downregulated." (PMID 34852024, 2021). "Overexpression of IGFBP2 has been found to promote GBM cell migration and invasion and contributes to glioma progression, recurrence, and poor survival in GBM." (PMID 32875483, 2020). "Recent studies have shown that patients with glioma have higher expression of some immunosuppression related genes, such as LGALS1 and IGFBP2, and blocking the expression of immune-inhibiting related genes can remodel the immunosuppression microenvironment." (PMID 33425739, 2020). "And as illustrated in the box plots, IGFBP2, EMP3, TIMP1 and SERPINE1 were all highly expressed in glioma tumor tissues, compared with the normal brain tissues." (PMID 32328202, 2020). "IGFBP2 was also found up-regulated in high-grade glioma and GBM and downregulated in IDH mutant glioma." (PMID 32070274, 2020). "As well as IGFBP-2, also IGFBP-3 improves glioma cell migration, invasion and proliferation in an IGF-independent manner." (PMID 33604294, 2020). "The prognostic significance of age related genes IGFBP2, EMP3, TIMP1 and SERPINE1 were further demonstrated in Kaplan-Meier survival analysis in glioma patients." (PMID 32328202, 2020). "Overexpressed insulin-like growth factor binding protein 2 (IGFBP2) promotes GBM cell migration and invasion, and contributes to glioma progression and cancer recurrence and poor survival in GBM." (PMID 31560714, 2019). "Evidence suggests that IGFBP2 engages the Akt signaling pathway and at least in some settings collaborates with platelet-derived growth factor β (PDGFB) in the development of glioma." (PMID 31296788, 2019). "Her2, AMPK-alpha, IGFBP2, and STAT5-alpha were highly expressed in IDH-wt grade II/III gliomas demonstrating the involvement of signaling cascades in these tumors." (PMID 29142297, 2017). "Because IGFBP2 is a well-established tumor-promoting factor in glioma, we investigated the role of NFIA in the regulation of IGFBP2 gene expression in glioma growth." (PMID 28323865, 2017). "To validate our finding of IGFBP2 as a specific prognostic marker of IDH-mutant glioma, we used an independent cohort of gliomas ranging from WHO grade II to grade IV with IDH status determined by immunohistochemistry against IDH1R132H." (PMID 27852048, 2017). "In fact, it was recently observed that the IGFBP2-neutralizing antibody leads to a reduction in the levels of phosphorylated EGFR, STAT3, and AKT in human glioma cells." (PMID 28036255, 2017). "Both high levels of serum IGFBP-2 and high tissue expression IGFBP-2 by both IHC and mRNA levels correlate with poor PFS and OS in gliomas, including glioblastoma multiforme (GBM)." (PMID 26217584, 2015).
glioma (continued). "We explore for the first time here the multiple roles of IGFBP2 and IGFI, their complex interactions with HIF1α, and their importance in glioma progression." (PMID 25884993, 2015). "Further evaluation of glioma samples, mostly focused in GBM, and of qualified databases, verified the presence of IGFBP2 proteolysis in gliomas and revealed a significant correlation between ADAMTS1 and IGFBP2." (PMID 24962328, 2014). "Recent studies in glioma implicate IGFBP2 in the activation of PI3K Akt pathway, integrin/ILK/NF-B network which drives glioma progression in mice and binding to integrin α5 that brings about increased migration and invasion." (PMID 23767917, 2013). "In brief, IGFBP-1, IGFBP-2, IGFBP-3, and IGFBP-5 have been shown to elevate PD-L1 expression on macrophages and tumor cells, leading to reduced immune response in gliomas, esophageal, and colorectal cancers." (PMID 41226289, 2025). "Therefore, we analyzed the correlation between STUB1 and IGFBP-2 in the CGGA database, and observed a positive correlation between them in gliomas." (PMID 39138166, 2024). "At present, the relationship between HOTAIRM1 and IGFBP2 in glioma cell and VM formation has not been investigated." (PMID 38012763, 2023). "In addition to CTLA4, PD-1, and LAG3, other immunosuppression-related genes, like IGFBP2 and LGALS1 are highly expressed in patients with glioma." (PMID 37399661, 2023). "Notably, the function of IGFBP2 in glioma cell malignancy and VM was found to be partially countervailed when overexpressing HOTAIRM1 in IGFBP2 silenced U251 cells or silencing HOTAIRM1 in IGFBP2 overexpressing U251 cells." (PMID 38012763, 2023). "Additionally, IGFBP2 can promote the formation of angiogenic mimics by regulating the expression of CD144 and MMP2 in glioma as well as enhancing nuclear EGFR-STAT3 signaling, which can be used as a therapeutic target for glioma." (PMID 35992105, 2022). "Additionally, iGFBP2 has been overexpressed within the stem cell compartment of GBM as an important factor in the clonal expansion and proliferative properties of glioma stem cells." (PMID 35992105, 2022). "Zhang obtained mRNA transcription information and clinical data of gliomas from the TCGA database and found that the expression of RAB42, SHOX2, IGFBP2, HIST1H3G, and IGF2BP3 negatively correlated with 5-years OS; also, IGF2BP3 expression significantly positively correlated with glioma grades." (PMID 34721530, 2021). "Accordingly, the combination of plasmatic IGFBP2 and anti-IGFBP2 antibodies levels has already been tested in lung, glioma, and colorectal cancer patients and found to improve not only diagnostic efficacy of the test, but also its prognostic power." (PMID 32093404, 2020). "Although the expression of IGFBP2 is controlled by epigenetic DNA methylation in glioma patients 42, we find no significant different methylation intensity of IGFBP2 and TIMP1 genes between old and young LGG patients." (PMID 32328202, 2020). "It turns out that IDH-mutant glioma patients generally manifest low IGFBP2 expression, which is associated with improved survival independent of IDH mutational status, whereas high IGFBP2 expression results in worse survival than in the IDH-wildtype group." (PMID 31296788, 2019). "Furthermore, IGFBP2 is overexpressed within the stem cell compartment of glioblastomas and is needed for clonal expansion and proliferation of glioma stem cells, and IGFBP2 may also contribute to tumor progression by enriching for glioma stem cells and boosting their survival." (PMID 31296788, 2019). "When IDH-mutant gliomas were stratified accordingly with 1p/19q co-deletion, we found no statistical differences in IGFBP2 expression between the two subtypes even though sharp differences remained between IDH-wildtype group and each subtype." (PMID 27852048, 2017).